GNB1 (G protein subunit beta 1)
Diseases named in the same sentence as GNB1 in open-access papers (continued):
Sharing a sentence is not in itself a finding about the gene and the disease.
microcephaly (3 papers, 2015 to 2023). A congenital or acquired developmental disorder in which the circumference of the head is smaller than normal for the person's age and sex. "Prior investigation of homozygous Gnb1 mutant mice demonstrated that Gnb1 is required for proper neurogenesis as Gnb1 knockout embryos developed neural tube defects or exhibited microcephaly and neonatal lethality." (PMID 37275776, 2023). "Other genes within the combined network are involved in neuronal progenitor cell proliferation, a common mechanism underlying microcephaly (RAC1 and GNB1) and neuronal development (CEBPB, L1CAM, MAPT, PAK2, SPTBN1, and YWHAE)." (PMID 25781962, 2015).
Parkinson disease (3 papers, 2017 to 2022). A progressive degenerative disorder of the central nervous system characterized by loss of dopamine producing neurons in the substantia nigra and the presence of Lewy bodies in the substantia nigra and locus coeruleus. "The protein interaction models build reference to the human disease complex of hereditary spastic paraplegias (HSPs) and possibly Parkinson's disease, rather than to multiple sclerosis, in addition to primary torsion dystonia by interaction to GNAL and to severe hypotonia by GNB1." (PMID 33329738, 2020).
retinoblastoma (3 papers, 2020 to 2024). A malignant tumor that originates in the nuclear layer of the retina. "Several rod photoreceptor-specific genes whose expression is known to be depleted in retinoblastoma were downregulated, but not NRL and GNB1." (PMID 33270844, 2020).
Alzheimer disease (2 papers, 2023). A progressive, neurodegenerative disease characterized by loss of function and death of nerve cells in several areas of the brain leading to loss of cognitive function such as memory and language. "In humans, Gnb1 expression has been shown to be increased in neurological diseases including Alzheimer’s disease." (PMID 38248237, 2023).
autism (2 papers, 2020 to 2024). Persistent deficits in social interaction and communication and interaction as well as a markedly restricted repertoire of activity and interest as well as repetitive patterns of behavior.
autism spectrum disorder (2 papers, 2023 to 2025). A spectrum of developmental disorders that includes autism, and Asperger syndrome. "Although autism spectrum disorders have been reported to be associated with mastocytosis, no clear association between mastocytosis and motor and intellectual delay has been reported with the exception of the case that detected de novo monoallelic mutations in the GNB1 gene." (PMID 36874330, 2023).
clear-cell renal cell carcinoma (2 papers, 2020 to 2022). "Like Akap9, Gnb1 is also implicated in kidney disease, where downregulation of the gene is associated with worsened prognosis of clear-cell renal cell carcinoma, as well as in resistance to tyrosine kinase inhibitor drugs in human models of kidney cancer." (PMID 32998684, 2020). "Furthermore, analysis of renal clear cell carcinoma showed that GNB1 was correlated with WASP family member 2 (WASF2), Neuropilin-1 (NRP1) and huntingtin interacting protein 1 (HIP1) of the vascular endothelial growth factor (VEGF) signaling pathway." (PMID 35193469, 2022).
colon cancer (2 papers, 2019 to 2020). "In colon cancer, positive expression of GNB1, which is part of the RAS-BRAF-MAPK-ERK pathway, was associated with longer OS." (PMID 32133296, 2020). "It was found that high expressions of NUDT21 (HR= 0.57, P = 0.023), GNB1 (HR=0.028, P=0.026), and CLINT1 (HR=0.6, P=0.043) were associated with better overall survival for colon cancer patients." (PMID 30881993, 2019). "Taken together, NUDT21, GNB1, CLINT1, and COL1A2 were considered as core genes with a close relationship to colon cancer." (PMID 30881993, 2019). "And we found that NUDT21, GNB1, CLINT1, and COL1A2 might be the potential core genes that play an important role in the development and prognosis in IIA stage colon cancer." (PMID 30881993, 2019). "Moreover, further deeply investigated molecular mechanism of NUDT21, COL1A2, GNB1, CLINT1, and colon cancer is necessary; it is also the limitation of this study." (PMID 30881993, 2019). "Finally, NUDT21, GNB1, CLINT1, and COL1A2 core gene were selected due to their correlation with the prognosis of IIA stage colon cancer." (PMID 30881993, 2019). "In conclusion, this study showed that NUDT21, GNB1, CLINT1, and COL1A2 might be the potential core genes that play an important role in the development and prognosis in IIA stage colon cancer." (PMID 30881993, 2019). "this study suggested that NUDT21, GNB1, CLINT1, and COL1A2 might be the core genes for colon cancer that play an important role in the development and prognosis of IIA stage colon cancer." (PMID 30881993, 2019). "Finally, NUDT21, COL1A2, GNB1, and CLINT1 closely related to the overall survival of colon cancer were selected as core genes." (PMID 30881993, 2019).
COVID-19 (2 papers, 2023 to 2025). A disease caused by infection with severe acute respiratory syndrome coronavirus 2. "GNB1 showed the largest increase in the plasma of PLWH with COVID-19, followed by PTPN6, FERMT3, and PSTPIP2." (PMID 40568587, 2025).
essential hypertension (2 papers, 2019 to 2025). Hypertension that presents without an identifiable cause. "Another novel KD GNB1 in “Insulin regulation” encodes a G protein β subunit, multiple mutations of which were found to affect the protein interface that binds Gα subunits (GNAS), which has been genetically and clinically associated with hypertension." (PMID 30931314, 2019). "Our search revealed both known KDs showing connections to hypertension or relevant conditions in one or more types of studies (99 KDs; such as GNAS, SLC2A3, IRS1, ADM, and SERPINE1) and relatively novel KDs in BP studies (such as SPTBN1 and GNB1)." (PMID 30931314, 2019).
hepatocellular carcinoma (2 papers, 2024 to 2025). A malignant tumor that arises from hepatocytes. "There were a number of limitations present in this study, including the use of Huh7 cells derived from a hepatoma, the lack of a secondary proteomic assay for GNB1, and the use of RHOA/RHOC antibody instead of a RHOC-specific antibody." (PMID 39066215, 2024).
infantile spasms (2 papers, 2022 to 2025). A rare epilepsy syndrome characterized by onset of epileptic spasms in infants between 2 and 12 months of age, and rarely up to 24 months. "Importantly, GNB1 has emerged as a potential candidate gene associated with West syndrome, and several individuals with GNB1-E have had West syndrome or infantile spasms." (PMID 40417225, 2025). "DEE, described in the literature as Ohtahara syndrome, infantile spasms, or EIFMS can be the epileptic presentation of GNAO1, GNB1, and PDE2A." (PMID 36003298, 2022). "Onset with tonic seizures or infantile spasms with EEG patterns of burst suppression or hypsarrhythmia has been described for GNAO1 and GNB1." (PMID 36003298, 2022).
Insulin resistance (2 papers, 2018 to 2025). Increased resistance towards insulin, that is, diminished effectiveness of insulin in reducing blood glucose levels. "Its centrality reinforces recent transcriptomic and functional data implicating GNB1 in pancreatic stress responses and insulin resistance, two hallmarks of T2DM pathogenesis." (PMID 40909129, 2025). "Hub genes such as GNB1, JAK1, and RPS3 dominated the T2DM network layer, suggesting critical roles in inflammatory signaling, insulin resistance, and translational control under metabolic stress." (PMID 40909129, 2025).
migraine with (2 papers, 2024 to 2025). "OPRM1 emerges as a pivotal hub, instigating the activation of GNAS and GNB1, subsequently influencing proteins such as RAMP1, RAMP2, RAMP3, CALCB, CALCR, and SLC5A2 all implicated in migraine attacks." (PMID 39215033, 2024). "The network analysis suggested that the specific proteins such as OPRM1, GNB1, and GNAS are interlinked and interacted with the migraine with aura pathological targets like RAMP154, RAMP255, RAMP356, CALCR57, CALCB58, ADM59, IAPP60, and SLC5A261." (PMID 39215033, 2024).
schizophrenia (2 papers, 2017 to 2021). A major psychotic disorder characterized by abnormalities in the perception or expression of reality. "Three separate studies discovered an increase in the GNB1 protein expression in the prefrontal cortex of schizophrenia patients." (PMID 34286132, 2021).
Stroke (2 papers, 2019 to 2023). Sudden impairment of blood flow to a part of the brain due to occlusion or rupture of an artery to the brain. "Using a pathway analysis, we found deletions in GNB1, PRKCZ, and GNG7 genes related to the alpha-adrenergic receptor signaling pathway that play a major role in determining the risk of an AF-related stroke." (PMID 30857284, 2019).
anhidrosis (1 paper, 2019). Lack of sweating or the ability to sweat when provoked by the appropriate stimulus. "De novo mutations in the GNB1 gene have been associated with cutaneous mastocytosis and neurodevelopmental delays, while mutations in the NTRK1 gene were found to cause anhidrosis and palmar hyperkeratosis." (PMID 31569353, 2019).
Anxiety (1 paper, 2023). Intense feelings of nervousness, tension, or panic often arise in response to interpersonal stresses. "The increased expression of brain Gnb1, which we also observed in the DOX-only-treated mice, has been linked to anxiety and depressive behavior." (PMID 38248237, 2023).
autosomal recessive cone rod dystrophy (1 paper, 2008). autosomal cone rod dystrophy is an autosomally recessive inherited retinal dystrophy that belongs to the group of pigmentary retinopathies. "Gao and colleagues have recently reported an association of GNB1 intronic variants with autosomal recessive RP, as well as autosomal recessive cone-rod dystrophy." (PMID 18776951, 2008).
brain cancer (1 paper, 2025). A primary or metastatic malignant neoplasm affecting the brain. "In our results, the role of epigenetics is further highlighted by the 10x levels of methylation seen in the seizure-associated locus in GNB1 for BOCA-FR or separately in the methylation fluctuations seen in HFM1 gene for paediatric brain cancer patients." (PMID 41345172, 2025).
cervical cancer (1 paper, 2020). A primary or metastatic malignant neoplasm involving the cervix. "Furthermore, GNB1 is a direct target of miR-326 and GNB1 overexpression antagonizes the inhibitory effect of miR-326 on cervical cancer cell growth and metastasis." (PMID 32766125, 2020). "Overexpression of GNB1 could antagonize the inhibitory effect of miR-326 on cervical cancer cell proliferation, migration, and invasion." (PMID 32766125, 2020). "The results indicated that GNB1 might regulate cervical cancer cell proliferation and invasion via controlling ERK signaling." (PMID 32766125, 2020).
Cortical blindness (1 paper, 2022). "Cortical blindness (4 patients) or oculomotor abnormalities including nystagmus (18 patients), strabismus (7 patients), and ophthalmoplegia (4 patients) have been described in nearly half of the GNB1 patients reported in the literature." (PMID 36003298, 2022).
diabetic nephropathy (1 paper, 2023). "Moreover, PAX8 is involved in the progression of diabetic nephropathy by targeting the miR-17-5p/STAT3 axis and osteoporosis by activating the autophagy of osteoblasts via the miR-1252-5p/GNB1 axis." (PMID 36831395, 2023).
female sterility (1 paper, 2025). "A gnb-1 deletion is associated with female sterility and induces conidiation in submerged culture." (PMID 39601596, 2025).
glioblastoma (1 paper, 2023). The most malignant astrocytic tumor (WHO grade IV). "Due to the increasing studies about novel circRNAs in kinds of malignant cancers, we furtherly studied the possible circRNAs derived from GNB1 and identified a novel circRNA termed circGNB1, which was overexpressed in glioblastoma and promoted malignant progression of GSCs." (PMID 37407973, 2023). "However, our results revealed that GNB1 did not facilitate glioblastoma progression significantly." (PMID 37407973, 2023).
glioma (1 paper, 2021). A benign or malignant brain and spinal cord tumor that arises from glial cells (astrocytes, oligodendrocytes, ependymal cells). "The positive clustering results of this study might be attributed to some characteristics of glioma tissue, such as the glioma-specific 1p19q co-deletion that affected the expression of GNB1, GNG5, GNG7, GNGN8, and GNG12." (PMID 34222011, 2021).
Harel-Yoon syndrome (1 paper, 2022). A syndromic neurodevelopmental disorder characterized by delayed psychomotor development, intellectual disability, truncal hypotonia, spasticity, and peripheral neuropathy. "Referring to the following databases: Berry DB, DECIPHER, OMIM, and DGV, 1p36.33 contains multiple functional genes such as SKI, GNB1, DVL1 and ATAD3A, among which ATAD3A gene is related to Harel-Yoon syndrome, and the possible clinical phenotypes include psychomotor retardation, mental retardation." (PMID 36471261, 2022).
Kabuki syndrome (1 paper, 2024). Kabuki syndrome (KS) is a multiple congenital anomaly syndrome characterized by typical facial features, skeletal anomalies, mild to moderate intellectual disability and postnatal growth deficiency. "Genetic analysis showed a GNB1 mutation, and the patient was diagnosed with Kabuki syndrome by a pediatrician, based on characteristic dysmorphic features." (PMID 39100058, 2024).
leiomyoma (1 paper, 2016). A well-circumscribed benign smooth muscle neoplasm characterized by the presence of spindle cells with cigar-shaped nuclei, interlacing fascicles, and a whorled pattern. "Similarly, among the spots recognized as GNB1, one corresponding to spot 5 (isoform 2 of GNB1) was increased in leiomyoma." (PMID 27070597, 2016).
leukemia (1 paper, 2023). A malignant (clonal) hematologic disorder, involving hematopoietic stem cells and characterized by the presence of primitive or atypical myeloid or lymphoid cells in the bone marrow and the blood. "Acquiring mutations in the GNB1 gene could cause resistance to tyrosine kinase inhibitors for leukemia." (PMID 36612298, 2023).
mast cell tumors (1 paper, 2025). "Recent genomic analyses reveal that these neoplasms frequently harbor mutations in genes associated with increased invasiveness and metastatic potential, including GNB1 mutations in 17.3% of mast cell tumors." (PMID 40723532, 2025).
mastocytosis (1 paper, 2023). A clonal myeloproliferative neoplasm characterized by the proliferation and accumulation of neoplastic mast cells in one or multiple organs or organ systems. "Herein, we describe the case of a Japanese male pediatric patient aged two years and six months who had cutaneous mastocytosis accompanied by motor and intellectual delay without the presence of GNB1 mutation." (PMID 36874330, 2023).
Mental Retardation, Autosomal Dominant 42 (1 paper, 2019). "In humans, heterozygous GNB1 (MIM 139380) missense, splice-site and frameshift pathogenic variants cause an autosomal dominant neurodevelopmental disorder, named MRD42 (Mental Retardation, Autosomal Dominant 42; MIM#616973)." (PMID 31817184, 2019).
neuroblastoma (1 paper, 2018). Neuroblastoma (NB) is the most common solid, extracranial childhood tumor. "GNB1 is also affected by APA in a PCF11-like manner upon depletion of BARD1 (see TREND-DB), one of the few factors in which germline mutations have been linked to neuroblastoma formation." (PMID 30552333, 2018). "Notably, GNB1 was previously identified as a marker for spontaneous neuroblastoma regression." (PMID 30552333, 2018).
osteosarcoma (1 paper, 2011). A usually aggressive malignant bone-forming mesenchymal neoplasm, predominantly affecting adolescents and young adults. "CDK 9 overexpression also increased proliferation of human osteosarcoma cell line U20S2, while CRK, CDK9, DCAF7, NEK6, GNB1, SPOP, and WW2 also increased proliferation in mouse fibroblasts." (PMID 21629697, 2011).
Pancytopenia (1 paper, 2023). An abnormal reduction in numbers of all blood cell types (red blood cells, white blood cells, and platelets). "The deletion fragment of 1p36.33-p36.32, particularly the loss of GNB1 gene, has been associated with the development of pancytopenia." (PMID 37946214, 2023).
retinal degeneration (1 paper, 2022). Degeneration of the retina. "The gene heatmap depicting the proteins involved in key functions such as significant activation of retinal degeneration in the KO group was attributed to two up-regulated (retinoschisin (Rs1) and ubiquilin-1 (Ubqln1)) and two down-regulated (Gucy2e and GNB1) proteins." (PMID 36359890, 2022).
Rod-cone dystrophy (1 paper, 2024). An inherited retinal disease subtype in which the rod photoreceptors appear to be more severely affected than the cone photoreceptors. "Gnb1, one of the NRL-binding genes, is enriched in rod photoreceptors and associated with rod-cone dystrophy." (PMID 39337887, 2024).
steatosis (1 paper, 2025). Increased lipid within the cytoplasm of cells. "Specifically, H4C1, OIT3, ANPEP, CCDC25 and KLHL41 were identified as potential biomarkers for steatosis, GP1BA as a candidate marker for MASH and C7, IGHD and GNB1 as potential biomarkers for fibrosis severity." (PMID 41301514, 2025).
urothelial carcinoma (1 paper, 2025). A malignant neoplasm derived from the transitional epithelium of the urinary tract (urinary bladder, ureter, urethra, or renal pelvis). "GNB1, the hub protein unique in the network specific to nonpapillary urothelial carcinoma, encodes the beta subunit of G proteins, which modulate transmembrane signaling, including that of the PI3K/AKT signaling pathway." (PMID 41342186, 2025). "In the PPI network specific to nonpapillary urothelial carcinoma, network B, we identified GNB1, RHOA, UBC, and FPR2 as hub proteins, which were involved in the PI3K/AKT signaling pathway." (PMID 41342186, 2025).